IGF1 (insulin like growth factor 1)
Diseases named in the same sentence as IGF1 in open-access papers (continued):
Sharing a sentence is not in itself a finding about the gene and the disease.
cancer (continued). "The association between life-long diminished IGF1 levels in congenital deficiencies and cancer protection highlights the central role of IGF1 in the etiology of malignancies." (PMID 33182502, 2020). "IGF-1 is associated with enhanced tumor cell division and anti-apoptosis behaviour (see Nutrient Levels Influence Mechanisms that Promote Cancer Development)." (PMID 32370764, 2020). "Higher levels of serum IGF-1 are linked with increased risk of several common cancers comprising breast, colorectal, and prostate." (PMID 32722232, 2020). "Recently, a host of studies explored the potential association between IGF‐1 gene rs2195239 polymorphism and various cancer risks." (PMID 32147868, 2020). "Future investigations using Asian‐specific genome‐wide association study estimates for IGF‐1 are required to obtain more accurate causal estimates for IGF‐1 and cancer in Asians." (PMID 32717139, 2020). "Some studies have been conducted on the biological functions of other IGF1 SNPs that appear to affect cancer susceptibility." (PMID 30654740, 2019). "Other studies focused on the role of FGF21 as the major mediator of the association between low cancer risk and a vegan diet, via downregulation of serum IGF-1 levels." (PMID 31408968, 2019). "Recently, many studies have described the relationship between the IGF1 gene rs2195239 and rs2162679 polymorphisms and the risks of various cancers." (PMID 30654740, 2019). "At the same time, many extracellular ligands (IGF-1, proinflammatory cytokines and the members of TGFβ family etc.)are associated with muscle atrophy induced by cancer cachexia." (PMID 30922397, 2019). "So we perform a meta-analysis to determine potential associations between IGF1 rs2195239 and rs2162679 polymorphisms and cancer risk." (PMID 30654740, 2019). "There are several lines of long‐standing evidence linking higher serum levels of IGF1 (associated with increased growth) and decreased serum levels of some IGFBPs (associated with suppressing growth through binding IGF1) with additional cancer risk." (PMID 31179642, 2019). "The epidemiological association between IGF1 and cancer incidence is conceptually consistent with the prosurvival and anti-apoptotic roles of IGF1." (PMID 31320996, 2019). "Epidemiological studies have shown that IGF1 is involved in tumor development, high concentrations of serum IGF1 are related to the increased risk of several types of cancer, supporting a potential role on the part of IGF1 in cancer development." (PMID 30654740, 2019). "It is noted that both height and body mass index (BMI) correlate with higher cancer risk and with increased circulating IGF1 levels and/or decreased IGFBP levels." (PMID 31179642, 2019). "Evidence of associations between IGFBP and IGF-1 levels and cancer phenotypes at the population level have been reported in the literature." (PMID 30895469, 2019). "Epidemiological studies conducted over the past two decades provide firm evidence that high circulating IGF1 levels correlate with an increased cancer risk." (PMID 31320996, 2019). "We performed the present meta-analysis to more precisely describe the relationship between the IGF1 rs2195239 and rs2162679 polymorphisms and cancer risk." (PMID 30654740, 2019). "Intriguingly, recent studies have shown that stromally derived IGF-1 promotes a cancer stem cell like phenotype in Kras mutated cell lines, via the PI3K→AKT signaling axis." (PMID 31452510, 2019). "There have been many well-designed cohort studies, such as the BPC3 cohort, and case-control studies regarding IGF1 polymorphisms and cancer risk in the past few years." (PMID 30654740, 2019). "Although we additionally expected to observe a decrease in IGF-1, which is associated with cancer risk and aging, declines in IGF-1 and IGFBP-1 in the evening did not quite reach statistical significance (both p = 0.11)." (PMID 31151228, 2019).
cancer (continued). "We conducted this meta-analysis to summarize the results of these studies regarding the IGF1 gene rs2195239 and rs2162679 polymorphisms and cancer risk." (PMID 30654740, 2019). "The linkage between high circulating IGF1 dosages and cancer risk has been firmly established by numerous epidemiological studies conducted over the past two decades." (PMID 31208077, 2019). "A number of important functional pathways were highlighted such as cancer microenvironment, Hypoxia metagene associated pathway, and IGF1 pathway." (PMID 31595147, 2019). "The relationship between the IGF1 gene rs2195239 and rs2162679 polymorphisms and cancer risk were evaluated using ORs and 95% CI in the allele, homozygote, heterozygote, dominant, and recessive models." (PMID 30654740, 2019). "In accordance with this notion, type 2 diabetes, hyperinsulinemia, and increased circulating IGF-1 are established risk factors for pancreatic and other types of cancers." (PMID 31277269, 2019). "It has been reported that rs1520220 G to C substitution leads to increased plasma IGF1 level, increasing cancer risk as a result." (PMID 30111277, 2018). "Diabetic patients possess a higher risk of developing cancers than healthy patients, which is partly due to increasing levels of circulating growth factors, such as insulin or insulin growth factor 1 and 2 (IGF-1 and 2)." (PMID 30186236, 2018). "The results of our meta-analysis demonstrate that the role of IGF1 rs1520220 in cancer susceptibility varies by ethnicity and cancer type and that rs1520220 increases cancer susceptibility in Asian populations." (PMID 30111277, 2018). "Several previous studies have shown that high levels of IGF-1 are positively associated with an increased risk of several cancers, including colorectal, lung, breast and prostate." (PMID 29758048, 2018). "In PDAC, cancer-associated fibroblasts produce IGF-1 under hypoxic conditions and promote tumor cell migration via IGF-1R signaling under hypoxia in vitro." (PMID 29475434, 2018). "In cancer cells, this pathway was also found to be associated with tumoral expression of mRNA for IGF-1 and the stimulation of proliferation and survival of cancer cells." (PMID 29983893, 2018). "One potential reason for the positive association between adult height and cancer mortality is explained by IGF-1, which are related to the promotion of cell proliferation and inhabitation of apoptosis." (PMID 29758048, 2018). "Many studies have reported that several IGF1 SNPs affect plasma IGF1 levels and thus influence the risk of cancer." (PMID 30111277, 2018). "The rs1520220 polymorphism in the insulin-like growth factor 1 (IGF1) gene has been reported to affect cancer susceptibly in several studies." (PMID 30111277, 2018). "IGF-1 levels can vary among healthy individuals depending on sex, age, and lifestyle factors, but their interpersonal variability is considered a cancer risk determinant." (PMID 30111747, 2018). "Cancer development, which is associated with higher serum IGF‐1 levels, is a cause of death in aged mice (Rincon, Rudin, & Barzilai, 2005)." (PMID 29943496, 2018). "We paid special attention to rs1520220 because it has been reported to be associated with plasma IGF1 levels in many studies and thus associated with cancer susceptibility." (PMID 30111277, 2018). "The ability of IGFBPs to limit the amount of free IGF-1 in blood partly explains the molecular mechanisms underlying cancer prevention by exercise." (PMID 30111747, 2018). "There seems to be an association between genetic variations in IGF-1 signalling pathways and cancer." (PMID 28954393, 2017). "Accordingly, serum IGF-1 levels have been linked to a higher risk of certain types of cancer, including breast, colorectal, and prostate cancer." (PMID 29036907, 2017). "Biomarkers IL-6 and IL-8, VEGF, MMP-9, MCP-1, IL-11, IGF-1, and Rantes are associated with different stages of cancer." (PMID 28763032, 2017).
cancer (continued). "Less is known around IGF-1 as a treatment modality due to some early concerns raised around cancer risk, although such linkage remains controversial." (PMID 28786951, 2017). "Low levels of IGF-1 are associated with higher mortality due to the increase in cardiovascular mortality, high IGF-1 values are associated with higher cancer mortality." (PMID 29375617, 2017). "It has been suggested that an increase in IGF1 levels is associated with malignant and non-malignant tumors, and can promote the proliferation and division of tumor cells." (PMID 29241458, 2017). "Epidemiological evidences indicate that insulin secretion rate and insulin-like growth factor-1 (IGF-1) level influence cancer risk and/or cancer prognosis." (PMID 28978182, 2017). "Similar to insulin, epidemiologic studies largely demonstrate positive associations between serum IGF-1 and cancer risk and mortality, principally among colon and postmenopausal breast cancers." (PMID 28959684, 2017). "According to some epidemiologic studies, patients with type 2 diabetes are at a higher risk of developing cancer due to the elevated activity of IGF-1." (PMID 28410237, 2017). "Several metabolic risk factors, including insulin and IGF‐1‐enhanced TRIB3 expression in a diversity of human cancer cells." (PMID 27038142, 2016). "Studies on different types of cancer suggest that high ‘normal levels’ of IGF-I (that is, IGF-1 levels at the highest terciles) are related to an elevated cancer risk." (PMID 27279011, 2016). "In spite of a consistent positive observation between IGF‐1 and risk of first primary cancers (especially breast, prostate, and colorectal), the evidence for the role of IGF‐1 in the development of SPCs is less clear." (PMID 27734632, 2016). "Further work is needed to analyze the association between CCL5 and IGF-1 staining in adipose tissue and cancer features of patient with ER positive cancer." (PMID 27027351, 2016). "Previous studies by us and others have found that exercise-induced cancer prevention is associated with a reduction of multiple hormones, especially for the mitogenic hormone IGF-1." (PMID 27509024, 2016). "In the present study, we evaluated the role of PKM2 in promoting the growth of cancers associated with aberrant IGF-1 signaling." (PMID 27340866, 2016). "Side‐effects of cancer treatment and possible underlying etiological mechanisms, such as IGF‐1 metabolism, are thought to be implicated in the development of second primary cancers (SPCs)." (PMID 27734632, 2016). "Previous studies found that the IGF1 rs5742714 polymorphism was associated with cancer risk and prognosis." (PMID 27976731, 2016). "Many epidemiology studies also mentioned IGF-1 level in plasma is associated with an increased risk of cancer." (PMID 27835910, 2016). "The levels of IGF-1 appear to correlate with cancer risk in human populations, and the high contents of IGF-1 are associated with increased mortality in the general population." (PMID 27144340, 2016). "Individual genetic variations in the IGF1 signaling pathway have been associated with the prognosis of several common cancers." (PMID 27144430, 2016). "Increased energy balance, which culminates in increased adiposity, changes the levels of hormones such as insulin, adiponectin, leptin and IGF-1, which is also associated with cancer including ovarian." (PMID 25895126, 2015). "In animals, dwarf, long-lived mice lacking the growth hormone receptor (GHR-/-) have reduced levels of IGF-1, are insulin sensitive despite obesity, and have decreased risk for cancer and diabetes." (PMID 25902704, 2015). "As noted in §4c, low levels of IGF-1 have been associated with a decreased incidence to several forms of cancer in animals and humans." (PMID 26056364, 2015). "Deficiency in GH receptor and congenital IGF1 deficiency are known to confer protection against cancer." (PMID 26682276, 2015).
cancer (continued). "The polymorphism of the promoter CA dinucleotide repeats is associated with IGF-1 serum level, birth weight and body height, and with diseases including diabetes, cardiovascular disease and cancer." (PMID 25384883, 2015). "Inhibition of the IGF-1 pathway suppresses ovarian cancer cell survival in vitro and in vivo in xenograft models, and its expression is associated with cancer progression." (PMID 26510816, 2015). "Various human epidemiological studies describe the correlation between circulating levels of IGF-1 coupled with IGFBPs and the risk of developing various cancers, lung, colon, breast, and prostrate." (PMID 25866791, 2015). "High serum concentrations of IGF1 are associated with an increased risk of several cancers, including breast, prostate, colorectal, and lung cancers." (PMID 26682276, 2015). "Epidemiological evidence supporting an association between disruption in insulin/IGF1 homeostasis and cancer mortality is strong, but complicated by multiple confoundment." (PMID 26284118, 2015). "Conversely, patients with congenital deficiencies in IGF-1 demonstrate a protective effect against cancer development." (PMID 25384883, 2015). "There is epidemiological data to suggest that insulin secretion rate and insulin-like growth factor 1 (IGFI) levels influence cancer risk and/or cancer progression." (PMID 25961014, 2015). "Overall, there remain concerns about the possibility of delayed posttreatment effects of heightened GH and IGF-1 on cancer risk." (PMID 26064078, 2015). "Studies evaluating IGF-1 circulating concentrations and cancer risk show important effects on cancer development and progression." (PMID 24829560, 2014). "Significantly, IGF-1 deficiency is a major contributing factor in lifespan prolongation especially in females and in protection from cancer." (PMID 25333772, 2014). "It has also been demonstrated that humans with growth hormone receptor deficiency also exhibit a high reduction of IGF-1 and insulin level resulting in a highly reduced incidence of cancer and diabetes mortality." (PMID 24883306, 2014). "High circulating levels of insulin and IGF-1 have been established as risk and prognostic factors for many cancers." (PMID 25026276, 2014). "Dysregulation of this pathway has been implicated in a myriad of diseases such as cancers, neurodegenerative diseases, and metabolic disorders, making the IGF-1 signaling pathway a prime target to develop therapeutic and intervention strategies." (PMID 25628647, 2014). "High circulating levels of IGF-1 have been implicated as a risk and a poor prognosis factor in cancers of the breast, uterus, prostate and colon." (PMID 25026276, 2014). "IGF-1 and its receptor have also been implicated in the development of cancer by activating pathways of cell survival and proliferation." (PMID 23668396, 2014). "Insulin-like growth factor-1 (IGF-1) is a potent survival factor and implicated in the development and progression of various cancers." (PMID 24595361, 2014). "With respect to aetiological mechanisms, our analysis for those cancers thought to be associated with IGF-1 showed a consistent increased risk, also when stratified by treatment." (PMID 25047238, 2014). "After stratification of all subjects by a history of cancer, IGF-1 was inversely associated with survival duration only in individuals with a positive history of malignancy, after adjustment for age, sex, HDL cholesterol, CVD and T2DM (P < 0.01)." (PMID 24618355, 2014). "The published evidence from epidemiological studies has revealed a correlation between elevated IGF-1 levels and an increased risk of cancer diagnosis." (PMID 23525758, 2013). "Although the population studies did not always come to the same conclusions, systematic reviews of these results led to the interpretation that circulating IGF-1 levels are indeed related to a risk of several common cancers." (PMID 23525758, 2013).
cancer (continued). "Although many cancer cells are critically dependent on IGF-1 signaling, it is likely that due to their inherent genome instability cancer cells can mutate and bypass this requirement for continuous proliferation." (PMID 23443494, 2013). "On the other hand, it is also possible that the high level of apoptosis in OSE, due to a low systemic level of IGF-1, is responsible for elimination of mutated cells and thus a lower incidence of cancer." (PMID 24063422, 2013). "The pathway, with oncogene PIK3CA and tumor suppressor PTEN (gene), is implicated in insensitivity of cancer tumors to insulin and IGF1, in calorie restriction." (PMID 23768168, 2013). "Further analysis of the 1903 upregulated genes in women grouped them in statistically significant functional clusters that included genes associated with cancer, IGF-1 signaling as well as other immune signaling pathways (p<0.05)." (PMID 23651648, 2013). "Especially a haplotype in the LD block 3 located in a downstream of the CA repeat has been suggested as a novel genetic variation associated with circulating IGF-1 level or cancer risk." (PMID 23530598, 2013). "Elevated plasma concentrations of IGF-1 or IGFBP-3 have been associated with several types of cancers, including breast, prostate and lung cancer." (PMID 24103397, 2013). "Elevated IGF-1 is related to an increased risk of developing several cancers including that of the breast, prostate, and colon." (PMID 22852056, 2012). "These people are invariably tall and well muscled but have a high risk of cancer resulting from the higher circulating levels IGF-1." (PMID 22506111, 2012). "Recently, insulin growth factor (IGF)-1 has been implicated as a major cancer risk factor and a target of potential for dietary intervention strategies for cancer prevention." (PMID 22418926, 2012). "A previous study proposed that higher IGF1 serum levels and lower IGFBP3 levels were associated with cancer risk; however, the intra-individual variability in circulating IGF1, IGF2, and IGFBP3 levels is genetically determined." (PMID 22347413, 2012). "It is known to all that IGF-1 is an important mitogenic and antiapoptotic peptide, which affects the proliferation of normal and malignant cells and elevated levels of IGF-I are associated with carcinogenesis and the progression of cancer." (PMID 22844419, 2012). "Other forms of circumstantial evidence include the observation that height and birth weight, which is related to the concentration of IGF-1 in the umbilical cord, are related to the risk of some cancers." (PMID 21696633, 2011). "Studies of single nucleotide polymorphisms in the IGF-1 axis genes indicate a potential relationship between SNPs and circulating levels but increased risk of cancer development with IGF SNPs is unclear." (PMID 21696633, 2011). "Individuals at the high end of the normal range of serum IGF-1 have more than double the risk of a subsequent cancer." (PMID 21696633, 2011). "IGF-1 has been consistently linked to increased cell proliferation and cell migration, elevating cell invasion and metastatic properties of cancer cells." (PMID 21849056, 2011). "Kallikrein proteins have been linked to many forms of cancer, and of particular note is their role in the Igf1-Akt survival pathway." (PMID 21961992, 2011). "Low IGF-1 serum levels associate to a decreased risk of cancer, but an increased risk of cardiovascular disease and neurodegenerative disease." (PMID 21418511, 2011). "Prospective epidemiologic studies provide evidence of a relationship between circulating IGF-1 and the risk of developing prostate, breast, colorectal and other cancers." (PMID 21696633, 2011). "Higher serum IGF-1 levels were associated with increased risk of cancer death in older community-dwelling men." (PMID 21699736, 2011). "Studies of patients with acromegaly or Laron dwarfisim have been used as proxies to identify cancer risk in relation to IGF-1 excess or deficiency." (PMID 21696633, 2011).